ENSG00000221498
Synonyms: LOC124900540
Gene: Small nucleolar RNA gene on chromosome 2 (183,064,235 to 183,064,346, reverse strand). Ensembl gene ENSG00000221498.
Gene Ontology:
Biological process: RNA processing
Cellular component: nucleolus
Homologues: Orthologues: zebrafish SNORA77B (48% identical). Paralogues in human: SNORA77B (79% identical), SNORA77 (77% identical).